IL6 (interleukin 6)
Diseases named in the same sentence as IL6 in open-access papers (continued):
Sharing a sentence is not in itself a finding about the gene and the disease.
cancer (continued). "Serum levels of IL-6, IL-8, and GROα/CXCL1 progressively increased with advancing inflammation-to-cancer progression in rats, whereas salivary expression peaks occurred during the inflammatory phase." (PMID 41415031, 2025). "Regular exercise reduces circulating pro-inflammatory cytokines such as IL-6 and TNF-α in cancer patients." (PMID 41583457, 2025). "Understanding the role of IL-6 at differentconcentrations and its interactions with cells in the TME can enhancethe efficacy of cancer immunotherapy and improve patient outcomes." (PMID 39471283, 2025). "Further research is warranted to establish the IL‐6 cytokine family control of the aberrant upstream and downstream regulation of muscle AMPK activity that is disrupted with cancer and leads to aberrant protein turnover regulation with cachexia." (PMID 40931444, 2025). "When FRα-CAR-T cells were co-cultured with FRα-expressing cancer cells in 2D and 3D cultures, CAF-derived IL-6 reduced CAR-T cell cytotoxicity by increasing PD-L1 levels." (PMID 40281554, 2025). "This action reduces the transcription of pro-inflammatory genes including TNF-α, IL-6, and COX-2, which are commonly upregulated in cancer-related inflammation." (PMID 41226270, 2025). "The serum IL‐6 and TNF‐α level in the LJFE‐treated group was significantly lower than that in the cancer cachexia group." (PMID 40672545, 2025). "To inspect the participation of CTCF in the transcriptional regulation of the IL6 gene, we downregulated CTCF mRNA expression by transitorily transfecting specific siRNAs against CTCF mRNA in both MCF7 and MDA-MB-231 cancer cells." (PMID 40143084, 2025). "These antibodies inhibit IL‐6‐mediated signaling cascades involving JAK and STAT3 across various cancer types." (PMID 40166646, 2025). "IL-6 has been identified as a dual inducer of MAPK/ERK pathway activation and EMT in many cancers, including HNSCC." (PMID 39858048, 2025). "This interaction stimulates the release of inflammatory mediators, including interleukin-6 (IL-6), interleukin-17 (IL-17), and TNF-α, which foster a pro-tumorigenic microenvironment that enhances cancer cell proliferation and metastatic potential." (PMID 40718835, 2025). "In contrast, seven out of ten anti-AD core targets (PTGS2, MAPK1, MAPK3, JUN, ESR1, IL6, and PIK3CA) followed the pathways in cancer." (PMID 40179089, 2025). "For example, studies show that CAFs secrete IL-6 and IL-11 to activate STAT3 signaling in cancer cells, enhancing survival and resistance to apoptosis." (PMID 40718440, 2025). "One of the mechanisms described for the anti-cancer effect of GB is reactive oxygen species (ROS) suppression in cancerous cells, as well as inflammatory cytokines such as TNF-α, IL-6, iNOS, and COX-2." (PMID 41226786, 2025). "In carcinoma patients, CRT-NP treatment enhanced MCP-1 serum levels whereas in STS patients GM-CSF, IL-2, IL-6 & IL-18 were enhanced." (PMID 40386779, 2025). "myCAFs are located in the periglandular region, whereas iCAFs (characterized by the secretion of IL6, IL11, and LIF and a stimulated STAT pathway) are distantly located from cancer cells and myCAFs." (PMID 38667297, 2024). "The core signaling pathways included pathways in cancer, the PI3K-Akt signaling pathway, and the AGE-RAGE signaling pathway in diabetic complications, involving genes such as AKT1, IL6, JAK2, and MAPK1." (PMID 39338337, 2024). "The secreted PGE2 and cytokines amplify the expression of cytokines (e.g., IL1, IL6, and IL8) in cancer cells, thereby activating their stemness." (PMID 38515582, 2024). "NF-κB signaling via expression regulation of multiple target genes (e.g., BCLXL, BCL2, BCLXS, TNF-α, IL6, XIAP, and VEGF) represents an essential cellular pathway that is extensively involved in acquired therapy resistance in cancer." (PMID 37789138, 2024). "Several agents targeting the IL-6/GP130 pathway have been developed and investigated for cancer treatment." (PMID 39451730, 2024).
cancer (continued). "The IL6/STAT3 axis also increases TDO2, and consequent KYN production leads to the activation of AhR in response to inflammation in various types of cancer." (PMID 39311710, 2024). "We did not observe significant changes in circulating cytokine levels (IL-6, IL-8, IL-10, MCP-1 and IP-10) in patients with cancer undergoing systemic treatment after three months of nutritional support with whey protein-based oral nutritional supplements." (PMID 38892006, 2024). "Serum levels of serum amyloid protein A (SAA), high-sensitivity C-reactive protein (hsCRP), interleukin-6 (IL-6), procalcitonin (PCT), prealbumin (PA), and ferritin, were measured to assess the effect of Omicron-related inflammation among cancer patients." (PMID 38902401, 2024). "This study demonstrated that the overexpression of Mcl-1 or IL-6-induced Mcl-1 upregulation reversed mitochondrial dysfunction, mitochondrial fission, and mitophagy in IMQ-treated cancer cells and protected them from IMQ-induced apoptosis." (PMID 39272918, 2024). "Cancer cells secrete growth factors and cytokines (including IL-6, IL-1β, TGF-β1, TGF-β2, FGF-2, and PDGF), which help in the remodeling of the ECM and the development of the TME in cancer cells." (PMID 39518022, 2024). "iCAFs are the significant source of IL6 in the PDAC TME, with the ability to activate the STAT3 pathway in cancer cells." (PMID 39358777, 2024). "IL-6 induces the expression of anti-apoptotic proteins, such as Bcl-2 and BCL-XL, in cancer cells, thereby enhancing their resistance to apoptosis." (PMID 39421736, 2024). "Overexpressed MCT-1 stimulates the IL-6/IL-6R/gp130/STAT3 axis, which promotes epithelial-to-mesenchymal transition and cancer stemness." (PMID 38505617, 2024). "To validate our findings, we recruited a cohort of 21 cancer patients for histological confirmation, revealing significant mRNA upregulation of STAT3, IL6, MMP9, MMP3, TGFB1, VEGF and HIF1A, coupled with downregulation of LHPP and PCK1, PTEN and BLC2." (PMID 39468431, 2024). "The authors further showed that crocin inhibited cancers by downregulating the transcription of cytokines such as tumor necrosis factor-α [TNF-α], nuclear factor-κB [NF-κB], interleukin-6 [IL-6], interferon-γ, COX-2, IL-1β, and inducible NO synthase [iNOS]." (PMID 38891276, 2024). "Enrichment of miR-93-5p in these exosomes, induced by IL-6, leads to MDSC differentiation into M2 macrophages, facilitating colitis-induced cancer development." (PMID 38566199, 2024). "The high level of serum inflammatory cytokines in elderly patients was capable of inducing cancer cell (MCF-7) proliferation, which was specifically related to IL-6 and IL-8 levels." (PMID 38715140, 2024). "Elevated levels of proinflammatory cytokines, such as interleukin 6 (IL-6) and tumor necrosis factor alpha (TNF-α), are known to enhance cancer cell proliferation and survival." (PMID 38610685, 2024). "Studies have shown increased concentrations of multiple cytokines, including interleukin 6, TNFα, interleukin 8, the cytokines MIF, TGFβ, interleukin 10 and interleukin 18 in patients with cancer." (PMID 39020272, 2024). "Under the influence of chronic inflammation, proinflammatory cytokines and chemokines such as IL-6, IL-17, and IL-23 secreted by immune cells stimulate fibroblasts within the TME, promoting cancer cell growth and survival." (PMID 38539448, 2024). "Several cytokines, including leptin, IL-1B, IL-6, IL-8, IL-23, IL-17, and IL-10, stimulate cancer progression, while others, including IL-2, IL-12, and IFN-γ, inhibit cancer proliferation and/or invasion." (PMID 37979099, 2024). "Active genes, including IL6, VEGFA, and MFGE8, appear to be common among CAFs across various origins and have a significant impact on cancer cell phenotypes." (PMID 39676864, 2024).
cancer (continued). "AT releases higher levels of adipose-derived cytokines, such as leptin, Interleukin-6 (IL-6), and CC-chemokine ligand 5 (CCL5), promoting cancer proliferation and invasion." (PMID 38800384, 2024). "IL-6, IL-8, and CCL2 secreted from neighboring Mφs have been shown to alter the phenotype of cancer cells." (PMID 38486225, 2024). "A paracrine loop between cancer cells and TAMs, whereby TAM derived IL-6 activates STAT3/GLUT3 pathway in cancer cells to preserve high CXCL8 levels was suggested." (PMID 39044824, 2024). "IL-6 was therefore further investigated for its known role in mediating resistance to chemotherapy in MPM and other cancers." (PMID 38791392, 2024). "TAMs exert their influence through the secretion of an array of bioactive molecules, including cytokines such as IL-6 and TGF-β, and various growth factors that synergistically activate EMT pathways in cancer cells." (PMID 39286635, 2024). "Pro-inflammatory cytokines, including IL-6, IL-8, and TNF-α, serve as pivotal mediators in the intricate crosstalk between stromal and cancer cells." (PMID 38406163, 2024). "The IL-6/STAT3 signaling pathway and TYRO3 collectively involve cancer cell survival, proliferation, and resistance to chemotherapeutic agents." (PMID 38431573, 2024). "A-FABP enhances IL6/STAT3 signal transduction, promoting cancer growth and metastasis by regulating the NF-κB/miR-29b pathway." (PMID 39192979, 2024). "EGFR induces PD-L1 via the IL-6/JAK1/STAT3 pathway 63, which reciprocally drives PD-L1 phosphorylation (Tyr112) to evade cancer immunosurveillance." (PMID 38505617, 2024). "During the tumor initiation process, cancer cells release a range of growth factors, including TGF-β, IL-6, and IL-13, which play a crucial roles in the activation of fibroblasts into cancer-associated fibroblasts (CAFs)." (PMID 39697341, 2024). "Both TNF-α and IL-6 signaling have been shown to play protumorigenic and prometastatic roles in BRCA, particularly with secretion from/to cancer cells." (PMID 39642223, 2024). "Above data indicated that SPOP depletion promoted the secretion of macrophage-derived IL-6 into TME, thereby contributing to the escalation of UBC cell proliferation and the induction of cancer stemness." (PMID 39479456, 2024). "Interleukin 6 (pro-inflammatory) can activate the JAK/STAT signalling pathways, preventing apoptosis and, along with TNF-α, facilitating angiogenesis and cancer growth." (PMID 38191592, 2024). "In response to Pt, fibroblasts secrete cytokines (IL-6, TGF-β) that promote epigenetically mediated cancer cell plasticity and transition to a resistant state." (PMID 38165032, 2024). "Elevated IL6 secretion in CAF-cancer cell cocultures leads to altered TIL profiles, with IL6 blockade reversing these effects." (PMID 38693104, 2024). "We did not observe significant changes in circulating cytokine levels (IL-6, IL-8, IL-10, MCP-1 and IP-10) in patients with cancer undergoing systemic treatment after three months of nutritional support with whey protein-based oral supplements." (PMID 38892006, 2024). "Measurement of systemic biomarker concentrations revealed statistically significant increases (p < 0.05) in all of the following biomarkers in the group of cancer patients relative to controls: blood platelets, NLR, PLR, SII, CRP, IL-6, IL-8, and TNFα." (PMID 38744744, 2024). "This is because the IL-6/STAT3 signaling pathway is activated in many chronic inflammatory diseases, such as cardiovascular disease and cancer." (PMID 38617550, 2024).
cancer (continued). "A recent systematic review shows that cancer patients engaged in various exercise regimens exhibited improvements in immunity, including reductions in TNF-α, CRP, IL-8, and IL-6, along with an increase in NK cells." (PMID 39064705, 2024). "Cancer cells produce a range of pro-inflammatory cytokines, including tumor necrosis factor-alpha (TNF-α), interleukin-6 (IL-6), and interleukin-1 (IL-1)." (PMID 39451734, 2024). "In the proposed model, upregulation of IL6 and TNFA, among many other mRNA targets of downregulated miRNAs, would affect cancer cell proliferation and migration of leukocytes." (PMID 39428471, 2024). "It inhibits inflammatory cytokines such as TNF-α, IL-6, and IL-1β, improves cognitive functions by regulating the NGF-BDNF-CREB signaling pathway, and shows antiproliferative effects on cancer cell lines like AGS, HT-1080, and HT-29." (PMID 39124930, 2024). "In the attempt to shed light on the process involved in Notch/NF-κB combined enhancement of MDSCs, we observed that it coincided with the considerable increase in the level of IL-6, which represents a major regulator of MDSC activity in cancer." (PMID 39337370, 2024). "With respect to the tumor microenvironment, it has been shown that cancer-associated fibroblasts and pro-tumorigenic macrophages secrete IL-6 that triggers STAT3 activation in CRC cells, and this leads to an increase in RAC1B expression in the cancer cells." (PMID 39001533, 2024). "IL-6 is frequently upregulated in different cancer types, including OCSCC31, and heightened IL-6 levels can potentially stimulate nodal and distant metastasis through PI3K/AKT/mTOR pathway activation." (PMID 38839809, 2024). "We identified several potential CHI3L1 target proteins, including VEGFA, TGF-β1, Cluster of Differentiation 74 (CD74), IL-6, inhibitor of DNA binding 3 (ID3), MMP9, CXCL8, and SPP1, in this type of cancer." (PMID 38177294, 2024). "Thus, GDF-15 may also influence cancer cachexia, like IL-6, through the AP network." (PMID 38824130, 2024). "In our study, the treatment of non-aggressive BCC with CM derived from MpEV-ATMSC induced the expression of IL6, IL8, and IL1α in these BCC, suggesting the involvement of the PGE2 signaling pathway in the ability of MpEV-ATMSC to induce cancer stemness." (PMID 38515582, 2024). "The regulation of cellular pathways, transcription factors, and cytokines, including IL-6/STAT3, SNAIL, TWIST, and zinc finger E-box-binding (ZEB), plays a pivotal role in the metastatic process of cancer." (PMID 38543002, 2024). "This shows that endogenous OPG can enhance pro-carcinogenic features in both cancer and stromal cells by activating the STAT3/IL-6 pathway." (PMID 39181873, 2024). "Monocytes secrete a variety of pro-inflammatory cytokines, such as interleukins IL-1, IL-6, IL-10, and TNF-α, which have been correlated with reduced survival and a worse prognosis in patients with malignant tumors." (PMID 39493767, 2024). "Elevated IL6 levels activate signaling pathways and upregulate checkpoint molecules PDL1 and CTLA4 expression in cancer cells, which leads to inhibition of T cell activity and serves to escape immune response." (PMID 39766086, 2024). "It has been shown that the SASP factors, including IL6 and IL8, promote EMT, invasion, and stemness induction in cancers including GICs." (PMID 39335106, 2024). "CAFs assert their pivotal role within this vicious cycle, actively shaping an inflamed neoplastic niche where IL-6, IL-11, LIF, and CXCL5 orchestrate an inflammatory phenotype that fuels cancer progression." (PMID 39609411, 2024). "In vitro study has demonstrated that PAI-1 on cancer cells binds TLR4 and promotes TGF-β secretion in macrophages by increasing IL-6 production via NF-κB activation." (PMID 38397187, 2024). "Transcription factors like NF-κB and STAT3, inflammatory enzymes such as COX-2 and MMP-9, and pro-inflammatory cytokines like IL-1, IL-6, IL-8, and TNF-α are crucial in inflammation-induced cancer." (PMID 39061221, 2024).
cancer (continued). "The presence of malignant tumors can incite an escalation in platelet (PLT) counts through the release of thrombopoietin (TPO) and interleukin-6 (IL-6)." (PMID 38439014, 2024). "Autologous primary prostate cells or cancer cell lines were inhibited by silencing STAT3 and IL-6 signaling using fludarabine, a STAT3 inhibitor, and tocilizumab, an IL-6 inhibitor." (PMID 39202020, 2024). "In the development and progression of cancer, AKT1, JUN, IL6, SRC, EGFR and BCL2 plays a critical role." (PMID 39011503, 2024). "We previously demonstrated that CD44+CD24− cancer cells are enriched in basal-like tumors compared with other breast cancer subtypes and that CD44+CD24− cancer cells have heightened IL-6/JAK2/STAT3 signaling activity compared with other tumor cells." (PMID 38297352, 2024). "Some studies and publications have reported a relationship between dysregulation of expression of some cytokines, including IL-1, IL-2, IL-4, IL-6, LPC2, TNF-α, etc., and incidence of cancer, cancer invasivity, and metastases." (PMID 38541074, 2024). "The prognostic implications of IL-6, IL-1RA, and s-gp130 levels extend beyond the TNM-generated cancer prognosis, offering potential clinical applications." (PMID 38672565, 2024). "IL-6, IL-8, TGF-β, and other molecules are also involved in stimulating osteoclast activity and supporting cancer cell survival and growth in bone." (PMID 39605887, 2024). "Of note, the potential systemic effects of IL-6 produced by the TME, including CAFs, on cancer wasting, cachexia, and paraneoplastic syndromes are detailed in the chapters “Functions of CAFs” and “Paraneoplastic syndromes”." (PMID 39676864, 2024). "We furthermore show that IL-6 and M-CSF are strong drivers of increased abundance of immune incompetent CD14+ DC3s in the context of cancer and show that pharmacological inhibition of the IL-6R and CSF1R has potential to improve immunotherapy." (PMID 38242119, 2024). "Elevated levels of IL-1β, IL-6, and TNF-α have been demonstrated to facilitate the development of cancer." (PMID 39594117, 2024). "In summary, JAK1 or JAK2 is activated by various receptors such as IL-6, IL-11, LIF, GPCR, TLRs, etc., in most cancer cells." (PMID 38172648, 2024). "These connective tissue cells are activated and transformed into CAFs by mechanical tension, cancer cell interaction, and M2 macrophage secretion, mainly due to TGF-β signalling but also via CXCL12, PDGF, IL-4, IL-6, and IGF-1 activity." (PMID 39337393, 2024). "Studies evaluating the expression of classic pro-inflammatory cytokines (TNF-α, IL-1β, IL-6, IL-17, IL-18, IL-33) in the spinal cord, PAG, and DRG revealed upregulation following inoculation of cancer cells to establish the BCP models." (PMID 38940936, 2024). "Chemokines and cytokines, such as IL6/IL6R and CCR2/CCL2, serve as fundamental regulators within the TME, which has been firmly established as a pivotal driving force in cancer progression." (PMID 38468260, 2024). "The BMI effect on IL-6 and leptin is consistent with the BMI effect on TNBC invasiveness, given that these two adipokines can stimulate TNBC cancer cell migration and invasiveness." (PMID 39408921, 2024). "Considering the importance of the IL6/GP130/STAT3 signaling pathway in tumorigenesis and progression, targeting this pathway is a promising approach to cancer treatment." (PMID 39152779, 2024). "Both MSCs and A431 cells secreted MIF, SERPIN1, IL-8, and CXCL1/GRO⍺, while CCL2 and IL-6 were only found in MSC cultures, and CCL5 and GM-CSF were only detected in cancer cell supernatants." (PMID 38674102, 2024). "Increased production of IL-1, IL-6, and TNF-α was observed in phytohemagglutinin-stimulated cultured peripheral blood mononuclear cells isolated from advanced cancer patients." (PMID 39114348, 2024). "Those cancers with high expression of PDPN, MMP2 and THY1 were enriched for immune-mediated pathways, such as inflammatory response, IFN response, and IL6-JAK-STAT signaling." (PMID 39335130, 2024).